INS (insulin)
Diseases named in the same sentence as INS in open-access papers (continued):
Sharing a sentence is not in itself a finding about the gene and the disease.
Insulin resistance (continued). "The same 8-week study also reports that plasma insulin and insulin resistance via homeostatic model assessment (HOMA-IR) improved significantly (within group) in older adults." (PMID 28431533, 2017). "As the liver is an insulin-sensitive organ and hepatic insulin resistance precedes peripheral insulin resistance, HepG2 cells were chosen as the insulin resistance model in vitro." (PMID 29096724, 2017). "Other results showed that UC-MSCs alleviate insulin resistance in rats with T2DM by regulating the expression of NLRP3 inflammasome in peripheral insulin target tissues." (PMID 28515792, 2017). "Insulin resistance is defined as a decreased tissue response to insulin-mediated cellular actions, and this condition is the inverse of insulin sensitivity." (PMID 28704413, 2017). "The most commonly proposed mechanism for the fructose-induced insulin resistance appears to be the diminished ability of insulin to suppress hepatic glucose output and decrease insulin receptor density apparent in skeletal muscle and liver." (PMID 28555043, 2017). "High insulin levels represent an adaptive process to insulin resistance at the onset of type 2 diabetes." (PMID 28298922, 2017). "CXC Ligand 5 (CXCL5) is a new cytokine which is secreted from white adipose tissue during obesity and by blocking insulin signaling pathway inhibits the activity of insulin and promotes insulin resistance." (PMID 29387827, 2017). "Consistently, inactivation of SOCS-3 in hepatocytes improves hepatic insulin action and steatosis in young mice, but at older age, these mice develop obesity and insulin resistance due to the activation of acute phase response and overt inflammation." (PMID 28233125, 2017). "Insulin resistance is the condition characterized by a lowered response of cells to circulating insulin." (PMID 29098064, 2017). "Because both peripheral and central insulin resistance are features of obesity, future studies driven to investigate the time course of peripheral insulin effects on metabolism during prolonged endotoxemia must be performed." (PMID 28677618, 2017). "This suggests that they managed to compensate for their higher insulin resistance for many years until a steep decline in insulin secretion (and probable beta cell exhaustion) in the 5–7 years before diagnosis." (PMID 28409212, 2017). "We also explored the association of adipokines with some pro- (interleukin-6, C-reactive protein, chitotriosidase) and anti-inflammatory markers (HDL-cholesterol, paraoxonase 1, 25-OH vitamin D) and insulin resistance indices (glucose, insulin, HOMA-IR index)." (PMID 28421328, 2017). "β-cells act in response to an augmentation in glucose with an augmentation in insulin, and this response is modulated by the severity of insulin resistance." (PMID 28881687, 2017). "AI also prevented the negative impact of the HFD on glucose homeostasis; fasting blood glucose and insulin levels were both reduced and the homeostasis model assessment of basal insulin resistance (HOMA-IR) value was decreased." (PMID 28805698, 2017). "We tried to evaluate the association between B-2 cells and insulin resistance by using the C-peptide HOMA model, which uses plasma C-peptide concentrations to reflect endogenous insulin secretion." (PMID 28491871, 2017). "Our data showed that dexamethasone-induced insulin resistance in mouse granulosa cells reduced insulin sensitivity, accompanied with an increase in phosphorylation of p44/42 mitogen-activated protein kinase." (PMID 29125859, 2017). "One trial reported improvements in insulin sensitivity as measured by the homeostasis model of insulin resistance (HOMA-IR) at 9 years of age (p = 0.02 for intervention effect) and between 15–20 years (ptrend = 0.005 for intervention effect)." (PMID 29149184, 2017).
Insulin resistance (continued). "Statistically significant reductions in insulin (6.5 uU/ml vs. 2.7uU/ml) and insulin resistance (HOMA-IR) (1.9 vs. 0.8) in the intervention compared to the usual care groups were reported in only a single study." (PMID 29216263, 2017). "We previously reported that the 5-day HFHC-diet induced insulin resistance in South Asians, whereas Caucasians were capable of maintaining peripheral insulin sensitivity." (PMID 28195217, 2017). "They found that hepatic diacylglycerol (DAG) content within cytosolic lipid droplets best accounted for insulin resistance, being responsible for 64% variability in insulin sensitivity." (PMID 28587303, 2017). "Our findings also imply that subjects with elevated insulin resistance have less elevation of CNR1 gene expression by glucocorticoids compared with insulin sensitive subjects, possibly due to the already elevated levels of CNR1 in insulin resistance states." (PMID 27858284, 2017). "Additional evidence has shown that μ-opioid receptor activation is associated with elevation of circulating levels of β-endorphin that ameliorates the post-receptor insulin signaling cascade that increases insulin resistance." (PMID 28748177, 2017). "Anti-Aa IgG antibody titer correlated positively also with fasting plasma insulin (P = 0.004, ρ = 0.41) and the homeostasis model of assessment of insulin resistance (HOMA-IR) (P = 0.001, ρ = 0.46)." (PMID 29066788, 2017). "In healthy controls treated with antipsychotics, there is evidence to suggest that OLZ increases serum insulin levels and simultaneously induces peripheral insulin resistance, even prior to any weight gain." (PMID 29403343, 2017). "Food intake, body weight gain, levels of plasma uric acid, glucose, insulin, homeostasis model assessment of insulin resistance (HOMA-IR), and triglyceride in KK-Ay/Ta mice were significantly higher than those in normal mice." (PMID 29115981, 2017). "Plasma IL-6, CRP, glucose, serum insulin, and homeostasis model assessment of insulin resistance were significantly greater in OO compared with OL and YL (P < 0.01)." (PMID 28911148, 2017). "Hyperinsulinism, another hallmark of PCOS, often secondary to insulin resistance, is considered to contribute to abnormal glucose metabolism in PCOS, since insulin normally suppresses blood glucose level." (PMID 29204121, 2017). "After adjusting for age gender and BMI, fasting glucagon levels were positively correlated with 2-h post-load glucose levels, the HOMA index of insulin resistance and fasting insulin levels, and were negatively correlated with IGF-1 levels." (PMID 28881681, 2017). "Insulin resistance is defined as a condition in which higher than normal insulin concentrations are needed to achieve normal metabolic responses or normal insulin concentrations fail to achieve a normal metabolic response." (PMID 28916790, 2017). "Because PI3K is a key component of the insulin signalling pathway, then inhibition of insulin signalling leads to insulin resistance and thus increased glucose levels in the blood." (PMID 28806782, 2017). "At the end of the experiment, the rats in group (D+/M–) are in a state of insulin resistance and still have the ability to secrete substantial amount of insulin." (PMID 29296189, 2017). "Skeletal muscle accounts for approximately 75% of whole-body insulin-stimulated glucose disposal, which explains the central role of muscle in the insulin resistance induced impairment of glycemic homeostasis, especially in the postprandial period." (PMID 28708105, 2017). "Owing to potential links with fasting insulin concentration, insulin clearance and insulin resistance, we investigated glucose homeostasis in Lyplal1tm1a/tm1a mice." (PMID 29084768, 2017). "Mice lacking osteocalcin exhibit glucose intolerance resulting from the coexistence of impaired insulin secretion and insulin resistance." (PMID 28168202, 2017).
Insulin resistance (continued). "We identified the following: 1) HGF expression was increased in insulin target organ, such as liver, SM, and gWAT, in WT mice fed an HFD, and inhibition of HGF by antibody exacerbated HFD-induced obesity, insulin resistance, and impaired insulin signaling." (PMID 28273932, 2017). "There are about 31 commonly impaired bio-processes (mainly: insulin resistance, insulin signaling pathway, oxidative stress, mitochondrial dysfunction, degradation of beta cells, neuron apoptosis, etc.), which are associated with both AD and T2DM." (PMID 28922161, 2017). "An animal study using rats provided in vivo evidence that human CRP plays an active role in inducing hepatic insulin resistance, which is at least partially achieved through impairment in the insulin signaling pathway." (PMID 28575103, 2017). "Briefly, BMI, systolic BP, CRP and estimated insulin resistance was consistently positively-, while estimated insulin sensitivity and β-cell function were consistently negatively, associated with the L/A ratio at each visit in univariate analysis." (PMID 28068986, 2017). "An animal study suggested that insulin resistance induced by a high sodium diet is related to impaired insulin-stimulated microvascular recruitment." (PMID 29253859, 2017). "One limitation is that the HOMA insulin resistance and β-cell function indices are based on glucose and insulin concentrations in a single fasting blood sample." (PMID 29255446, 2017). "Insulin resistance is characterized by the failure of target cells to respond to normal levels of circulating insulin, and this condition is related to cardiovascular disease." (PMID 28492722, 2017). "The results showed SNPs linked with homeostasis model assessment of insulin resistance (HOMA-IR) and fasting insulin near ATP10A (rs6576507 and rs8026527) and CACNA1D (rs1401492)." (PMID 28515345, 2017). "A diet rich in unsaturated fatty acids, present in oilseeds, plays an important role in the prevention of insulin resistance, increasing insulin affinity for the receptors." (PMID 29065507, 2017). "This progressed to obesity (~12% increased body weight) and sustained insulin resistance (~38% increased AUC insulin) by age 12 m." (PMID 27647861, 2017). "Changes in fasting serum insulin concentrations and the homeostasis model assessment of insulin resistance (HOMA2-IR) were different between the two groups (P ≤ 0.044)." (PMID 28753161, 2017). "Because a major manifestation of insulin resistance is a decreased insulin-stimulated glucose disposal by skeletal muscle, we have focused our attention on the mechanisms of insulin resistance in this tissue." (PMID 28915272, 2017). "Potential mechanistic evidence is mainly based on fiber content, which has been shown to improve insulin sensitivity and insulin secretion to overcome insulin resistance." (PMID 28397016, 2017). "Insulin resistance in obesity arises from the combination of altered functions of insulin target cells (e.g., liver, skeletal muscle, and adipose tissue) and the accumulation of macrophages that secrete pro-inflammatory mediators in adipose tissue." (PMID 28273932, 2017). "Insulin resistance is defined as the impaired systemic metabolic response to insulin, which includes glucose uptake and metabolism, suppression of lipolysis and promotion of lipogenesis, as well as protein and glycogen synthesis." (PMID 28566439, 2017). "Thermogenic defects are associated with insulin resistance in BAT, and cold stress has been shown to stimulate the insulin-signaling pathway in BAT to improve glucose homeostasis and insulin sensitivity." (PMID 29058611, 2017).
Insulin resistance (continued). "Demonstration of a role for impaired insulin clearance in insulin resistance in human disease is emerging." (PMID 28184213, 2017). "Taken together, our data indicates that culture of both cell lines in HS results in a more insulin‐sensitive phenotype and allows the role of insulin resistance in steatosis development to be investigated." (PMID 29263118, 2017). "The induction of insulin resistance in the brain has been supported by the elevated brain contents of insulin and RAGE, as well as the decreased level of insulin receptors." (PMID 28832656, 2017). "Insulin resistance is an adverse health condition in which muscle, fat, and liver cells have a reduced sensitivity to insulin." (PMID 28786989, 2017). "To test insulin resistance, we performed an insulin tolerance test in control WT mice, and WT mice that received 124 μM steviol for 2 weeks via the drinking water (∼0.5 mg per day per mouse)." (PMID 28361903, 2017). "Increased fasting serum insulin levels represent a compensatory mechanism to overcome insulin resistance." (PMID 28658284, 2017). "ANADET repealed insulin resistance, improved blood insulin levels, increased hemoglobin, and improved inflammation parameters." (PMID 28163748, 2017). "T1D results in insulin-dependency after autoimmune mediated β-cell destruction, whereas the more prevalent T2D is a complex metabolic disorder resulting from insulin resistance and progressive β-cell inactivation." (PMID 28424732, 2017). "Several in vivo studies suggested that oxidative stress is associated not only with diabetic complications but also with insulin resistance and that antioxidant therapy improves insulin sensitivity in a diabetic animal model." (PMID 28607575, 2017). "TC and EV treatments to FF diet fed mice decreased the insulin resistance and improved the insulin sensitivity, which led to reduced circulatory fatty acid load resulting in low triglyceride content and LD accumulation." (PMID 29371918, 2017). "Further, the HFD animals also developed insulin resistance as indicated by the higher circulating levels of insulin in this group." (PMID 29025435, 2017). "Hepatic insulin resistance is characterized by a blunted suppression of hepatic glucose production in response to insulin, which is secondary to the impairment of insulin signaling." (PMID 28072825, 2017). "Glucose tolerance and insulin resistance were evaluated by intraperitoneal glucose tolerance test and insulin tolerance tests." (PMID 28555111, 2017). "Insulin resistance is characterized by the presence of normal numbers of insulin receptors (IR), significantly increased levels of insulin (INS), but decreased INS activity." (PMID 29207492, 2017). "The benefit in control of T2DM after RYGB appears to be mediated by a decrease in insulin resistance, an increase in early insulin response, and the total insulin secretion to glucose load." (PMID 27783367, 2017). "According to literature, high plasma levels of leptin are related to insulin resistance, and leptin reduces insulin sensitivity in isolated adipocytes." (PMID 28830524, 2017). "Type 2 diabetes is characterized by beta cells being unable to produce sufficient amounts of insulin in the context of insulin resistance." (PMID 28742858, 2017). "As compared to CK-18, FGF-21 improves insulin sensitivity and insulin resistance in obesity animal models." (PMID 28326329, 2017). "A primary effect of metformin is the suppression of the hepatic gluconeogenesis and glucose output, and to increase the peripheral glucose uptake, with consequent reduction in insulin resistance and circulating insulin levels." (PMID 29184536, 2017). "Collectively, we find that genes link directly to insulin secretion and indirectly, through communication with other genes, to insulin resistance and T2DM." (PMID 28179884, 2017).
Insulin resistance (continued). "Insulin cannot promote normal fat storage, resulting in excess circulating free fatty acids that, in turn, further contribute into insulin resistance in muscle, leading to diabetes-like syndrome in PKR1ec−/− adipocytes." (PMID 28447033, 2017). "ERK2 activation is critical for the normal feedback mechanism of insulin signaling and its aberrant activation contributes to insulin resistance in PCOS." (PMID 29245975, 2017). "hSeP treatment induced the increase of insulin resistance and the decrease of insulin secretion, while AE2 administration improved these unfavourable effects." (PMID 29162828, 2017). "The correlations between hs-CRP level and total cholesterol, HDL-cholesterol, triglyceride, and insulin levels in this study can be explained by the role of cytokines in insulin resistance and lipid accumulation." (PMID 28234943, 2017). "Insulin resistance, described as the fundamental failure to respond appropriately to insulin, mainly affects the target tissues of insulin, particularly skeletal muscle and liver, but also adipose tissue and brain." (PMID 29286343, 2017). "Type 2 diabetes (T2D) is characterised by hyperglycaemia resulting from defective insulin secretion, insulin resistance, or both." (PMID 28754022, 2017). "Studies have reported attenuation of insulin resistance (IR) by improving phosphorylation of the insulin signalling pathway." (PMID 29038536, 2017). "It is well-known that both spaceflight and bed rest induce a set of subclinical diabetogenic effects in humans, such as insulin resistance, decreased glucose tolerance, increased glucose level in plasma and reduced insulin." (PMID 28529490, 2017). "Insulin plays a major role in the regulation of hepatic gluconeogenesis and glucose production and in case of hepatic insulin resistance, it is precisely the impairment of this regulated pathway that majorly contributes to increased glucose output." (PMID 28814771, 2017). "The treatment of T2DM-induced impairment of insulin signaling pathway with NSO decreased insulin resistance and repaired brain insulin signaling pathway." (PMID 28505155, 2017). "No time by treatment interaction for fasting blood glucose, fasting insulin, glycated hemoglobin, homeostatic model assessment of insulin resistance, or glucose area under the curve for the frequently sampled oral glucose tolerance test were observed." (PMID 27521509, 2017). "Type 2 diabetes (T2D) is a heterogeneous disorder characterized by insulin resistance and impaired insulin secretion." (PMID 28585545, 2017). "Our discovery that the correlation between the SSR marker Sweat Peak with the PTG-TP marker of insulin resistance suggests that the sweat gland nerve or unmyelinated C fiber function is influenced by insulin production." (PMID 28616394, 2017). "Before the onset of type 2 diabetes beta cells start to proliferate and increase the biosynthesis and secretion of insulin to compensate for peripheral insulin resistance and glucose intolerance." (PMID 28770320, 2017). "The renin-angiotensin-aldosterone system’s deleterious axis increases the production of inflammatory cytokines and raises oxidative stress; consequently, exacerbating insulin resistance and decreasing insulin secretion." (PMID 28098780, 2017). "As insulin resistance is a common hallmark of NASH, fasting blood glucose (FBS) and insulin levels were determined to investigate the effect of salidroside on these parameters." (PMID 28255329, 2017). "FFAR4 variants, particularly rs17108973, can modulate the effect of n-3 FAs on insulin-related traits, particularly insulin resistance, after a six-week supplementation with high doses of n-3 FAs." (PMID 29113108, 2017). "Cross–sectional studies have shown that OSA impairs glucose tolerance and/or insulin sensitivity, as measured by Homeostasis Model Assessment-Insulin Resistance index (HOMA-IR), even after adjusting for body mass index (BMI) and even in non-diabetic patients." (PMID 28384333, 2017).